HIF1A (hypoxia inducible factor 1 subunit alpha)
Diseases named in the same sentence as HIF1A in open-access papers (continued):
Sharing a sentence is not in itself a finding about the gene and the disease.
liver fibrosis (continued). "For example, microRNA-322/424 regulates LSEC dedifferentiation by targeting the CUL2/HIF-1α pathway to promote liver fibrosis, and correcting these aberrant microRNAs can alleviate liver fibrosis." (PMID 37999580, 2023). "In the current study, we explored clinical specimens obtained from cirrhosis patients and a mouse model of liver fibrosis to demonstrate upregulated HIF-1α, decreased CAT activity, and H2O2 accumulation in fibrotic regions." (PMID 36797395, 2023). "Moderate cholesterol can also activate Nrf-2 and HIF-1α and promote hepatocyte proliferation and liver regeneration, improving hepatic fibrosis." (PMID 36843951, 2023). "HIF-1α can promote HSCs activation; therefore, reducing HIF-1α expression in liver fibrosis plays an important role in alleviating liver fibrosis." (PMID 38077794, 2023). "Many studies have shown that HIF-1α mediates oxygen homeostasis, regulates the expression of multiple hypoxia stress protein genes, and significantly increases the expression in hepatic fibrosis tissues." (PMID 38074679, 2023). "HIF-1α has been reported to play an important role in liver fibrosis, kidney fibrosis, and myocardial fibrosis, but its effect in PF is unclear." (PMID 35682354, 2022). "In this study, we provide evidence that sorafenib ameliorates CCl4‐induced liver fibrosis by triggering ferroptosis in HSCs through HIF‐1α/SLC7A11 pathway." (PMID 34811833, 2022). "This showed the potential role and involvement of HIF-1α in liver fibrosis development in vivo for the very first time." (PMID 36523459, 2022). "In nonalcoholic fatty liver disease, HIF-1α has also been reported to promote liver fibrosis by acting on the PTEN/p65 pathway." (PMID 35682354, 2022). "These investigations supplied crucial insights into the effects of HIF-1α over-expression in hepatic fibrosis." (PMID 36523459, 2022). "For checking the impact of the activated HIF and hypoxia upon HSCs functional activity the in vivo function of HIF-1α upon HSCs in the liver fibrosis progression was evaluated by numerous studies." (PMID 36523459, 2022). "Sorafenib triggers hepatic stellate cell ferroptosis by inhibiting the HIF‐1α/SLC7A11 pathway to attenuate liver fibrosis." (PMID 34811833, 2022). "These research studies suggested a significant role of HIF-1α in the progression of liver fibrosis, its cell-specific role in the etiology of the fibrotic process of the liver still needs further investigation." (PMID 36523459, 2022). "Previous investigations focused on the role of HIF-1α in the pathogenesis of tumors; however, several reports proposed its role in liver fibrosis by the modulation of a set of genes involved in collagen synthesis and angiogenesis." (PMID 36297027, 2022). "Most impressively, new, and profound insights into HIF-1α role in treating hepatic fibrosis were revealed by breakthroughs of its function and mechanism in the development of hepatic fibrosis." (PMID 36523459, 2022). "Following BDL, mice carrying hepatocyte-specific HIF-1α conditional deletion showed a significant reduction in liver fibrosis versus control mice, as evaluated in terms of the transcript and protein levels of type I collagen and α-smooth muscle actin (αSMA)." (PMID 34359934, 2021). "The combination of celecoxib and octreotide decreased thioacetamide-induced liver fibrosis in rats by inhibiting the phosphorylation of the extracellular signal-regulated kinase (p-ERK)/HIF-1α/vascular endothelial growth factor (VEGF) pathway." (PMID 35187072, 2021). "Studies have shown that hypoxia directly contributes to the progression of liver fibrosis and that HIF-1α represents an important regulator of hepatic stellate cell (HSC) activation by modulating autophagy." (PMID 34288817, 2021).
liver fibrosis (continued). "At the same time, HIF1a expression changes positively affect the induction of extracellular matrix deposition and angiogenesis in liver fibrosis." (PMID 34853322, 2021). "Yiguanjian Decoction has anti-angiogenic effects in CCl4-induced liver fibrosis mice through inhibiting HIF-1α/VEGF signaling pathway and improving the hepatic hypoxic microenvironment." (PMID 33933107, 2021). "The use of this inhibitor resulted in a significant decrease of HIF1α as well as of liver fibrosis and angiogenesis." (PMID 34359934, 2021). "miRNA-322/424 exacerbates hepatic fibrosis by influencing the CUL2/HIF-1α axis to regulate angiogenesis." (PMID 34867446, 2021). "Recent studies identified that hedgehog signalling promoted prospero homeobox protein 1 (PROX1) expression in liver fibrosis, which inhibited HIF‐1α ubiquitination via a deubiquitinase called ubiquitin specific peptidase 19 (USP19)." (PMID 35187072, 2021). "In NASH mice, the significant upregulation of HIF‐1α in hepatocytes increased proportion of M2 macrophages and promoted liver fibrosis and HCC." (PMID 35187072, 2021). "Deletion of Hif1a protects against liver fibrosis in mouse models of both fibrotic liver disease, such as mice subjected to BDL, and models of NAFLD." (PMID 34692739, 2021). "In a rat model of CCl4-induced liver fibrosis, ligustrazine alleviated hepatic injury, angiogenesis, and vascular remodelling by decreasing the level of HIF-1α." (PMID 35187072, 2021). "In conclusion, these findings demonstrated that miR-98 targeted HLF and attenuated hepatic fibrosis through the HIF-1α/TGF-β/Smad2/3 signaling pathway." (PMID 32637414, 2020). "A study initially verified that curcumin protected against CCl4-induced hepatic fibrosis by suppressing HIF-1α via the ERK-dependent signaling pathway." (PMID 33082829, 2020). "Combined, these data support a role for HIF-1α in promoting EndMT in vitro and liver fibrosis in vivo." (PMID 32478075, 2020). "Astonishingly, these findings are in line with seminal reports demonstrating that CXCL1, CXCL11, HIF1A, COL4A1, and FN1 are implicated in liver fibrosis." (PMID 32161843, 2020). "Oroxylin A prevented from angiogenesis of LSECs in liver fibrosis via inhibition of the YAP/HIF-1α signaling pathway." (PMID 33082829, 2020). "In mice, the hypoxia-inducible factor 1α (HIF-1α) generated upon oxygen deprivation has been demonstrated to be a crucial factor in collagen cross-linking, contributing to liver fibrosis in NAFLD." (PMID 32085378, 2020). "Another study showed that the induction of genes involved in epithelial to mesenchymal transition (EMT) is another way through which HIF1-α can promote liver fibrosis progression." (PMID 32764403, 2020). "Paeoniflorin, as one typical TCM was tested in liver fibrosis and proved to affect HIF-1α through mTOR-dependent pathway." (PMID 31105564, 2019). "Another independent study demonstrated that conditional deletion of HIF1A in hepatocytes attenuates liver fibrosis induced by a high trans-fat diet in mice, which is another model of liver fibrosis." (PMID 31221962, 2019). "Our findings demonstrated that GGCLT treatment improved liver fibrosis caused by BDL in mice, in part through a decrease in HIF-1α-induced elevation of inflammation, oxidative stress, and angiogenesis-related factors." (PMID 31455001, 2019). "In the mouse BDL model, mice deficient in HIF-1α developed less fibrosis and had fewer activated fibroblasts, suggesting that HIF-1α is an important driving force for the development of liver fibrosis during chronic injury." (PMID 31035686, 2019). "A recent study showed that inhibiting HIF activity through the disassembly of the HIF-1α-p300/CBP protein-protein interaction was considered to be a potential therapeutic target for hepatic fibrosis." (PMID 29862292, 2018). "For example, the IH of OSA has been shown to contribute to liver fibrosis via recruitment of HIF-1α signaling." (PMID 29755400, 2018).
liver fibrosis (continued). "Recently, the upregulation of HIF-1α was documented to be concerned with activation of HSCs and liver fibrosis." (PMID 29862292, 2018). "Studies of a specific model of cholestasis revealed that chronic liver injury activates HIF-1α in macrophages, regulating the production of mediators of liver fibrosis." (PMID 29955245, 2018). "Sirius Red/Fast Green staining showed that silencing HIF-1α or HIF-2α separately inhibited liver fibrosis compared with the control group." (PMID 28112200, 2017). "Our results showed that silencing HIF-1α or HIF-2α alone inhibited liver fibrosis, but silencing HIF-1α plus HIF-2α achieved a further attenuation in fibrosis in BDL groups." (PMID 28112200, 2017). "Normoxia-active HIF-1α or HIF-2α prevented the inhibitory effect of VHL on liver fibrosis, indicating that attenuating fibrosis via VHL is HIF-1α- and HIF-2α-dependent to some extent." (PMID 28112200, 2017). "Recent evidence indicates that HIF-1α is activated in the liver subjected to bile duct ligation (BDL), whereas liver fibrosis is reduced in HIF-1α-deficient mice." (PMID 28112200, 2017). "Sirius red staining of mouse livers demonstrated that Hif1a-/-hep mice had markedly reduced liver fibrosis compared to wild-type controls." (PMID 28030556, 2016). "Both wild type and HIF-1α-deleted mice show increase in serum bile acids, but HIF-1α deleted mice were protected from increases in liver fibrosis." (PMID 26098428, 2015). "In vivo experiments using bile duct ligated (BDL) Hif-1α-deficient and control mice, showed less fibrosis in Hif-1α-deficient mice, as observed by lower levels of α-SMA and type I collagen, thus further indicating its importance during liver fibrosis." (PMID 26283969, 2015). "There is no specific evidence illustrating a connection between curcumin and the HIF-1α/ERK pathway in rat liver fibrosis induced by CCl4." (PMID 25407718, 2014). "Recently, it was reported that Hif-1α has also profound effect on liver fibrosis through regulating expression of genes for angiogenesis and collagen synthesis, but the regulatory mechanisms of Hif-1α in liver fibrosis is still unclear." (PMID 24040163, 2013). "In addition, RT-qPCR results also demonstrated that HIF-1α mRNA levels were considerably increased in CCl4-induced mouse liver fibrosis tissue, relative to the control group, and ACBA treatment led to a significant decrease in HIF-1α mRNA expression." (PMID 41375167, 2025). "During liver fibrosis, HSCs respond to hypoxic stimuli, upregulating HIF-1α expression." (PMID 40791591, 2025). "The purpose of this study was to investigate whether ACBA could target HIF-1α to inhibit hepatic M1 macrophages, thereby alleviating LPS-induced liver fibrosis in mice." (PMID 41375167, 2025). "This study aimed to investigate whether ACBA decreases macrophage glycolysis and pro-inflammatory phenotype polarization by inhibiting HIF-1α to alleviate hepatic fibrosis in mice." (PMID 41375167, 2025). "Thus, an immoderate HIF-1α regulates the M1 macrophage polarization through glycolytic pathways, which is one of the pivotal mechanisms for liver fibrosis." (PMID 41375167, 2025). "Notably, the higher NIC dose further amplified the recovery, increasing the expression of these proteins by 3.52-, 3.85-, 4.48-, 2.47-, and 2.46-fold, while HIF-1α expression was reduced by 57.89% compared to the TAA-induced liver fibrosis group." (PMID 41365955, 2025). "At 24 h post-CIDR removal, 20 over-represented canonical pathways were identified and the top pathways were HIF1α signaling, Axonal guidance signaling, Amyotrophic lateral sclerosis signaling, Hepatic fibrosis/hepatic stellate cell activation, and Clathrinid-mediated endocytosis signaling." (PMID 38547106, 2024).
liver fibrosis (continued). "Recent research has unveiled that a nanomicellar carbon monoxide-releasing molecule, SMA/CORM2, can mitigate liver fibrosis induced by a high-fat methionine- and choline-deficient (HF-MCD) diet by inhibiting the hypoxia-inducible factor 1-alpha (HIF-1α)-mediated inflammatory cascade." (PMID 38790620, 2024). "Sorafenib evokes HSC ferroptosis to attenuate liver fibrosis by regulating the HIF-1α/SLC7A11 axis." (PMID 38756248, 2024). "Noteworthy, in liver fibrosis, Gli1 has been clarified as a promoter for HIF-1α." (PMID 36811777, 2023). "Resisting angiogenesis in hepatic fibrosis through the PDGFRB/ERK/HIF-1α and VEGFA/AKT/eNOS signaling pathways may serve as a promising therapeutic approach for treating hepatic fibrosis." (PMID 38155904, 2023). "The same study showed that the miR-345-5p–HIF1α axis might be a potential therapeutic target for liver fibrosis." (PMID 37511368, 2023). "However, microRNA-322/424 promotes angiogenesis to aggravate hepatic fibrosis by activating the HIF-1α signaling." (PMID 38074679, 2023). "Unfortunately, there has been little research on whether inhibiting Src activation can also reduce HIF-1α expression in liver fibrosis." (PMID 38077794, 2023). "Chronic liver injury caused by cholestasis may lead to anoxic areas in the liver that may induce HIF-1α activation, which further regulates a variety of fibrotic mediators, and stimulates the overproduction of collagen and liver fibrosis." (PMID 37432229, 2023). "This may reveal that hypoxia generated by the metabolism of ethanol may increase the expression of HIF-1α in hepatic cells after subjecting to CCL4, prompting HIF-1α to play a significant role in liver fibrosis progression." (PMID 36523459, 2022). "Results proved that liver fibrosis was reduced greatly in HIF-1α knockout mice." (PMID 36523459, 2022). "Moreover, sorafenib was shown to attenuate liver fibrosis by triggering HSCs ferroptosis via hypoxia-inducible factor (HIF)-1α/SLC7A11 signaling in a carbon tetrachloride (CCl4)-induced mouse liver fibrosis model." (PMID 36703745, 2022). "In nonalcoholic fatty liver disease model, knockout HIF‐1α specifically in hepatocyte could reduce liver fibrosis." (PMID 34811833, 2022). "Moreover, in ferroptosis-induced brain injury and liver fibrosis models, HIF-1α suppressed ferroptosis." (PMID 35906211, 2022). "Myeloid HIF1α has been shown to promote the progress of liver fibrosis." (PMID 34853322, 2021). "Increasing evidence shows the role of HIF-1α in the process of liver fibrosis." (PMID 35187072, 2021). "Hypoxia has been shown to be an important inducing factor of inflammation and fibrosis in chronic liver disease; HIF-1a is a key transcription factor for liver fibrosis and is involved in the biliary ligation (BDL) and carbon tetrachloride- (CCL4-) induced liver fibrosis in rats." (PMID 33880382, 2021). "HIF-1α promotes liver fibrosis in NAFLD by activating phosphatase and tensin homolog (PTEN)/p65 signaling pathway, which may be targeted for therapy." (PMID 33499194, 2021). "On the other hand, studies have found that Prospero Homeobox 1 (PROX1) can inhibit the expression of HIF-1α: CCl4-induced liver fibrosis mice, curcumin inhibits LSECs angiogenesis by regulating the Glis-PROX1-HIF-1α signaling pathway, thus slowing down the development of liver fibrosis." (PMID 33933107, 2021). "HIF-1α can also participate in liver fibrosis by regulating liver sinusoidal endothelial cells." (PMID 33639908, 2021). "Moreover, the study of liver fibrosis models revealed that HIF-1a deficient mouse models have shown reduced collagen-I and a-SMA levels (liver fibrosis), suggesting hypoxia influence of collagen-I (ECM) secretion." (PMID 34885188, 2021). "In recent animal experiments, it has been found that isocyanate B can inhibit the production of a variety of pro-fibrotic factors through the miRNA-122/HIF-1α signaling pathway, and has a significant protective effect on non-alcoholic steatohepatitis-related liver fibrosis." (PMID 33933107, 2021).
liver fibrosis (continued). "Similar to KEGG, most of the common enriched IPA pathways of DEGs and DNBs were associated with fibrosis, including hepatic fibrosis/HSC activation, HIF1α signalling, inhibition of matrix metalloproteases (MMP), LXR/RXR activation and retinol biosynthesis (Figure 4C1)." (PMID 33269546, 2021). "The loss of PHD1, plus the downregulation of Keap1 (Kelch-like ECH-associated protein 1), a sensor of oxidative stress, favors the constitutive activation of HIF1-α, protecting hepatocytes against ischemia/reperfusion-induced liver injury and preventing liver fibrosis." (PMID 32764403, 2020). "HIF-1α elevation in HSCs mediates their survival and may contribute to an increase in liver fibrosis." (PMID 32566088, 2020). "Our study found that miR-98 could suppress HLF expression in HSCs and attenuate liver fibrosis by inhibiting the HIF-1α/TGF-β/Smad2/3 axis." (PMID 32637414, 2020). "Activation of Hh signalling could exacerbate mouse liver fibrosis and pathological angiogenesis via increasing the levels of HIF‐1α and VEGF‐A; meanwhile, it has a positive effect on PROX1 expression." (PMID 32119185, 2020). "Inhibition of HIF-1α activity dampened liver fibrosis in mice." (PMID 32478075, 2020). "Since HIF-1α appeared to be essential for BRG1 recruitment to the TWIST promoter, we asked whether HIF-1α inhibition would be sufficient to block EndMT and liver fibrosis." (PMID 32478075, 2020). "Similarly, the effect of HIF-1α inhibition by small-molecule compound on liver fibrosis is too great to be ascribed to the blockade of endothelial-mesenchymal conversion." (PMID 32478075, 2020). "However, there has been little exploration of the relationship between proliferation of portal fibroblasts and a hypoxic microenvironment (e.g., upregulation of HIF-1α) at the beginning of cholestatic liver fibrosis." (PMID 31455001, 2019). "It has been reported that HIF-1α is activated in mice with BDL-induced liver fibrosis." (PMID 31455001, 2019). "The purpose of this study was to investigate whether Ger-Gen-Chyn-Lian-Tang (GGCLT) suppresses oxidative stress, inflammation, and angiogenesis during experimental liver fibrosis through the hypoxia-inducible factor-1α (HIF-1α)-mediated pathway." (PMID 31455001, 2019). "The pathological role of HIF1A has been well documented in the pathogenesis of liver fibrosis." (PMID 31221962, 2019). "However, following a short-term (6-week) supplementation of high cholesterol and cholic acid (the designated NASH model), chronic production of NO by iNOS induced liver fibrosis, HIF-1α stabilization, and DNA damage in WT mice." (PMID 29955245, 2018). "In addition, the silencing of HIF-1α resulted in primary inhibition of HSC/MFs migration, which suggested a significant function of HIF-1α in the development of liver fibrosis." (PMID 29862292, 2018). "It has however been reported that HIF-1α expression was transiently increased in the mouse livers after high fat/sucrose diet, and expression is also increased in the bile duct ligation model of liver fibrosis and in ethanol induced fatty liver." (PMID 29190746, 2017). "To extend our findings, we next tested whether VHL-mediated inhibition of liver fibrosis was HIF-1α- or HIF-2α-dependent." (PMID 28112200, 2017). "The effect of HIF-2α silencing in attenuating liver fibrosis was significant compared with HIF-1α silencing in CCl4 groups, indicating that HIF-2α may play a dominant role in toxic liver fibrosis." (PMID 28112200, 2017). "However, silencing HIF-1α alone also attenuated liver fibrosis, so the role of HIF-1α cannot be ignored." (PMID 28112200, 2017). "Herein, the present study demonstrated that YC-1 administration improved liver fibrosis in mice, which was caused by a BDL through, at least in part decrease of HIF-1α-induced inflammatory cells infiltration, angiogenesis and bile duct epithelial cell proliferation." (PMID 29156788, 2017).